ZNF667-AS1 (ZNF667 antisense RNA 1)
Synonyms: MORT
Gene: Long non-coding RNA gene on chromosome 19 (56,477,250 to 56,504,362, forward strand). Ensembl gene ENSG00000166770.
Diseases named in the same sentence as ZNF667-AS1 in open-access papers:
ZNF667-AS1 is named in the same sentence as 11 diseases in open-access papers, as found by Europe PMC text mining. Sharing a sentence is not in itself a finding about the gene and the disease. The quoted sentences say what the papers report.
cancer (3 papers, 2018 to 2021). A tumor composed of atypical neoplastic, often pleomorphic cells that invade other tissues. "Based on TCGA data for 17 cancer types, epigenetic silencing of lncRNA MORT (ZNF667-AS1) in epithelial cells from 15 cancer types was extracted." (PMID 33921525, 2021).
ZNF667-AS1 also shares sentences with these, for which no sentence is quoted: tumor (2 papers); breast carcinoma (1); cervical cancer (1); leukaemia (1); lymphoma (1); mesothelioma (1); myocardial infarction (1); renal carcinoma (1); sarcoma (1); uterine carcinosarcoma (1).